PRL (prolactin)
Diseases named in the same sentence as PRL in open-access papers (continued):
Sharing a sentence is not in itself a finding about the gene and the disease.
Insulin resistance (continued). "Previous studies have found low serum PRL to be related to higher rates of metabolic syndrome, and insulin resistance assessed by homeostatic model assessment (HOMA-IR) in men without diabetes; these two conditions are major precursors for developing type 2 diabetes." (PMID 38760578, 2024). "Thus, in our study, we used the prolactin threshold of 14.9 ng/mL, which is in accordance with a previous review about the incidence of insulin resistance in patients with PCOS." (PMID 39768704, 2024). "Insulin resistance together with lower circulating PRL levels may act synergistically to impair beneficial metabolic action of PRL in adipocytes, and thereby exaggerate adipocyte hypertrophy and dysfunction." (PMID 36993818, 2023). "Central dopamine and prolactin levels plays a key role in the glucose homeostasis control, and their dysregulation could lead to the pathognomonic central insulin resistance depicted in the “ominous octet”." (PMID 36993818, 2023). "The central dopamine and prolactin levels plays a key role in the glucose homeostasis control, and their dysregulation could lead to the pathognomonic central insulin resistance depicted in the “ominous octet”." (PMID 36993818, 2023). "Pathologic elevated levels of PRL (>70ng/ml) leads to increased insulin resistance." (PMID 36993818, 2023). "This would suggest that, in women prior to FA food fortification, FA may have had a protective effect against insulin resistance by promoting PRL secretion." (PMID 37049394, 2023). "Cui Nai Ling, traditional veterinary medicine with seme vaccariae as one of the active ingredients, could upregulate prolactin levels, regulate insulin resistance, and improve the glucose and lipid metabolism disorders in rats." (PMID 38026663, 2023). "PRL have been shown to promote adipose differentiation and enhance adipocyte hyperplasia and may be a potential therapeutic target against insulin resistance and metabolic syndrome." (PMID 36993818, 2023). "Upon conducting miRNA-mediated KEGG pathway analysis, several pathways including the prolactin signal pathway, insulin resistance, autophagy, the insulin-signaling pathway and the FoxO-signaling pathway were found to be significantly enriched in the calf affected by fat necrosis." (PMID 37443947, 2023). "Moreover, KEGG analysis showed that genes were mainly enriched into the cancer pathway, MAPK pathway, prolactin pathway, insulin resistance, and thyroid hormone pathway." (PMID 36636603, 2023). "Significant differences were observed in baseline variables, including BMI, AFCs, LH levels, LH/FSH ratio, E2 levels, prolactin levels, testosterone levels, homeostasis model assessment of insulin resistance (HOMA-IR) levels and fasting insulin levels (P < 0.05)." (PMID 37388214, 2023). "Given that both are associated with increased insulin resistance and GDM (and consistent with higher GDM incidence in STOP), higher PRL and hPL may be essential to promote insulin secretion in response to cues brought on by alterations in 1C metabolism." (PMID 37049394, 2023). "Similarly, both PRL and hPL were reported to increase maternal insulin resistance, although their role in beta cell adaptation is greater." (PMID 37049394, 2023). "In this context, the hypothesis that biomarkers produced during lactation, such as prolactin (PRL), could improve markers of insulin resistance (MIR) has emerged." (PMID 37711904, 2023). "Clinical data show an association of high very prolactin levels with increased prevalence of obesity and metabolic disorders such as dyslipidemia, glucose intolerance, and insulin resistance, and many of these disorders are improved by normalizing prolactin levels with dopamine agonists." (PMID 35757410, 2022). "Moreover, numerous studies have documented that PRL affects metabolism homeostasis through the regulation of key enzymes and transporters related to insulin resistance, hypertension or coronary syndrome." (PMID 33716958, 2021).
Insulin resistance (continued). "Elevated PRL also has an effect on blood glucose, increasing peripheral insulin resistance." (PMID 32655635, 2020). "PRL levels in men and women with impaired glucose tolerance, type 2 diabetes and insulin resistance and children with metabolic syndrome and obesity are lower, and might increase after lifestyle intervention in obese children." (PMID 32477263, 2020). "Nonetheless, significant improvements in weight, BMI, waist circumference, lipid profile, and insulin resistance were seen in both hypogonadal and eugonadal patients, suggesting that PRL may play a direct role in mediating these adverse metabolic effects." (PMID 31847209, 2019). "Experimental studies indicated that PRL has effects on food intake, body weight gain, and insulin resistance via inhibiting adiponectin and IL-6 production in adipose tissue, which may lead to type 2 diabetes mellitus." (PMID 28384295, 2017). "Alternatively, our results appear to reflect non-diabetic conditions, and may therefore indicate mechanisms linking PRL to type 2 diabetes mellitus (insulin resistance) more precisely than the previous study." (PMID 28384295, 2017). "Significant increases in serum insulin concentration, homeostasis model assessments of insulin resistance, luteinizing hormone, luteinizing hormone/follicle-stimulating hormone, fasting blood sugar, testosterone, and prolactin were observed in the case group compared to the controls." (PMID 29387827, 2017). "Similarly, fastinginsulin also showed significant positive correlationswith insulin resistance (r=0.981) and prolactin(r=0.542, P<0.01)." (PMID 27123196, 2016). "Second, a major (side) effect of haloperidol treatment is elevation of prolactin levels which may contribute to the induction of glucose intolerance and insulin resistance." (PMID 21603181, 2011). "Altogether, these findings suggested that inadequate PRL suppression by dopamine agonists might alter metabolic homeostasis, triggering excessive body fat accumulation, insulin resistance and metabolic syndrome, and thus promoting the increase in overall cardiovascular risk." (PMID 39078526, 2024). "However, pathologically high levels of prolactin may alter glucose tolerance, disrupt glucose signaling in pancreas, and induce insulin resistance." (PMID 35757410, 2022). "As PRL concentrations increase within the physiologic range, IL-6 release into the tissue decrease, leading to an inflammatory state that might aggravate insulin resistance." (PMID 36471299, 2022). "Increased prolactin levels in patients with type 2 diabetes may also serve as a compensatory mechanism against hyperglycemia, as prolactin is essential for enhancing pancreatic-cell function and overcoming insulin resistance in this condition." (PMID 36762321, 2022). "In contrast, other studies have shown an inverse association between serum PRL levels and metabolic parameters such as cardiovascular events, cardiac remodeling, diabetes, metabolic syndrome, homeostasis model assessment (HOMA) for insulin resistance, and adverse lipid profiles." (PMID 28384295, 2017). "Furthermore, a cross-sectional study in 345 healthy volunteers aged 30-55 years showed a negative association of PRL with insulin resistance and a doubled risk of prevalent MetS per SD decrease in PRL." (PMID 23517652, 2013). "The enhanced prolactin signalling in adipocytes, highlighted through increased prolactin receptor expression during pregnancy in the current study, may contribute to the development of insulin resistance." (PMID 24236022, 2013). "Additional outcome measures included plasma 25-hydroxyvitamin D, fasting plasma glucose, glycated hemoglobin (HbA1c), the homeostatic model assessment of insulin resistance (HOMA-IR), prolactin, gonadotropins, and sex hormones." (PMID 41900862, 2026).
Insulin resistance (continued). "Cabergoline-induced normalization of prolactin may therefore lead to restored total and free testosterone levels to improve glycemic control via a wide range of mechanisms including via reductions in inflammation and weight gain – factors that further drive insulin resistance." (PMID 39906261, 2025). "Prolactin was higher when HDL-C was high but lower with increasing age, weight, and markers of insulin resistance and liver health." (PMID 39425884, 2024). "Moreover, for the last sub-analysis, we used a pre-defined prolactin cut-off value of 14.9 ng/mL in accordance with a previous review, which might not have necessarily been the optimized cut-off for the prediction of insulin resistance in our study population." (PMID 39768704, 2024). "PRL and PRLR are related to fat metabolism and promote insulin resistance by activating the Janus kinase 2/signal transducer and activator of transcription 5 (JAK2/STAT5) signaling pathway and increasing triglyceride deposition." (PMID 36993818, 2023). "In the KEGG enrichment analysis, insulin resistance and many diabetes-related signaling pathways were identified, such as the HIF-1, PI3K/Akt, prolactin, Rap1, Ras, calcium, and FoxO signaling pathways." (PMID 36159557, 2022). "This surgery results in reduced BMI and waist circumference, with improved insulin resistance and glucose tolerance, vitamin D, SHBG, FSH and total and free testosterone, inhibin B and AMH, and reduced estrogen and prolactin." (PMID 34829704, 2021). "It has been reported that serum PRL levels were significantly decreased in patients with PCOS, possibly leading to insulin resistance and damage of beta-cells." (PMID 33716958, 2021). "Indeed, the second trimester is a period of increased insulin resistance thought to be due at least in part to the higher levels of several hormones resulting from the growing placenta, including circulating placental lactogen, progesterone, prolactin, placental growth hormone, and cortisol." (PMID 34126994, 2021). "It is likely that the high expression of MAPK9 is involved in integrating insulin production, insulin resistance, and MAPK and prolactin production signaling to increase lipid synthesis in the liver." (PMID 31456815, 2019). "It was found that Triglycerides, Cholesterol, LDL, VLDL, prolactin, T3, FT3, and insulin resistance were significantly different in both overall comparisons and between two depression groups (all P < 0.05)." (PMID 31747876, 2019). "TSH showed positivecorrelations with BMI, hsCRP, fasting glucose,fasting insulin, insulin resistance, LH/FSH ratioand prolactin (r=0.173, P<0.05, r=0.757,r=0.772, r=0.499, r=0.583, r=0.492, r=0.693, respectively and P<0.01)." (PMID 27123196, 2016). "This disparity may be attributed to insulin resistance or inflammation in GDM women, which may diminish prolactin responsiveness and lead to delayed lactogenesis and breastfeeding initiation and maintenance." (PMID 38732598, 2024). "On the other hand, PRL is essential for adipose tissue differentiation and Prlr- mice with HFD demonstrated reduced adipocyte hyperplasia, increased adipocyte hypertrophy and increased insulin resistance." (PMID 36993818, 2023). "PRL is also essential for adipose tissue differentiation and Prlr- mice with HFD demonstrated reduced adipocyte hyperplasia, increased adipocyte hypertrophy and increased insulin resistance." (PMID 36993818, 2023). "In the future, we will investigate whether the abnormal metabolic indicators, insulin resistance, and PRL levels of co-DM patients have a deeper unexplored influence mechanism on the protective effect of aripiprazole on hyper-prolactin." (PMID 36329924, 2022). "Pups consuming the obesogenic-hypoprolactinemic milk develop obesity, excessive adiposity, severe insulin resistance, and fatty liver at weaning; whereas when their HFD-fed mothers or themselves receive exogenous PRL during lactation, metabolic alterations are ameliorated." (PMID 36213259, 2022).
Insulin resistance (continued). "Negative correlation was seen between rs1137101 and triglycerides in Tunisians, while homeostasis model assessment of insulin resistance (HOMA-IR) and insulin correlated with rs2025804 and rs1137101 among Bahraini subjects, and rs1137101 correlated with estradiol and prolactin." (PMID 33245096, 2021). "In contrast, we identified decreased expression of selected genes involved in insulin resistance in adipose tissue, including TLR3, FOS, and PRL, which could induce insulin sensitivity." (PMID 26089598, 2015). "As the insulin resistance improved as a result of the treatment, the relations involving TSH, cortisol and GH appear the most affected along with the drastic changes in relations with PRL." (PMID 24852517, 2014). "On contrary, HOMA-IR, as a measure of insulin resistance, did not change after treatment with dopamine agonists, and PRL concentrations did not correlate with HOMA-IR change or decrease in glucose, respectively." (PMID 23517652, 2013). "Though insulin resistance was not directly measured in this study, we determined the balance between insulin, growth hormone, and prolactin as an indirect indication of this phenomenon." (PMID 24244349, 2013). "Similarly, the women with PCOS who had insulin resistance also exhibited higher prolactin levels than their counterparts without insulin resistance." (PMID 40362476, 2025). "In addition to prolactin, we assessed thyroid-stimulating hormone (TSH), thyroid antibodies, and glucose homeostasis markers: fasting glucose, the homeostatic model assessment 1 of insulin resistance ratio (HOMA1-IR), and glycated hemoglobin (HbA1c)." (PMID 39852352, 2025). "These discrepancies could be due to the fact that both high and very low PRL levels have been recently linked to negative metabolic outcomes, while moderately elevated PRL levels have beneficial effects on various metabolic aspects, including insulin resistance." (PMID 40362476, 2025). "Additionally, prolactin may contribute to insulin resistance, independent of conditions such as PCOS, suggesting a more direct metabolic role." (PMID 41510476, 2025). "Interestingly, GH2, which promotes insulin resistance, was lower in obese women in SCOPE (in line with lower PRL and hPL) but not in STOP." (PMID 37049394, 2023). "Another dopamine receptor agonist, cabergoline decreased waist circumference, plasma lipids, glycated haemoglobin, insulin and the homeostatic model assessment of insulin resistance (HOMA-IR) and this effect, observed regardless of the degree of reduction in prolactin levels, was dose-dependent." (PMID 25239203, 2015). "Based on the significant correlations of PRL with BMI and HOMA-IR, we wanted to further investigate whether there was also a significant difference in prolactin levels in the women with PCOS with and without overweight/obesity and insulin resistance, respectively." (PMID 40362476, 2025).
Anxiety (133 papers, 2007 to 2026). Intense feelings of nervousness, tension, or panic often arise in response to interpersonal stresses. "A decrease in PRL levels during this critical window impairs neurogenesis and is associated with deficits in offspring retrieval and increased anxiety-like behavior in the postpartum period." (PMID 40565372, 2025). "In men with sexual dysfunction, low serum PRL levels have been associated with atherogenic erectile dysfunction, premature ejaculation, and anxiety symptoms." (PMID 39172174, 2024). "This study also showed that the downregulation of NTS1 in the PrL caused anti-anxiety-like effects in stressed rats." (PMID 36829752, 2023). "We believe that the present study provides compelling evidence demonstrating that maladaptation of distinct top-down circuits from the PrL underlies hyperalgesia and anxiety-like behaviors, respectively, under chronic pain conditions." (PMID 36917193, 2023). "The interaction of hormones, facilitated by oxytocin and prolactin, fosters a strong maternal bond, reduces the risk of postpartum depression and anxiety, and enhances self-confidence." (PMID 38021634, 2023). "For example, salivary cortisol is associated with prolactin level in mothers of very premature babies over 6 weeks of expressing milk and measures of anxiety such as the State-Trait Anxiety Index (STAI) correlate with oxytocin level at 8 weeks after birth." (PMID 35906655, 2022). "The PrL has previously been shown to contribute to pain-related anxiety, deficiencies in reward processing, and avoidance behaviour." (PMID 33555256, 2021). "The study also evaluated the effect of intranasal OT and/or DAP on plasma levels of OT, and prolactin; which has previously been linked with anxiety in dogs." (PMID 31632314, 2019). "Studies on inbred lines of rodents have shown an association between elevated levels of PRL and increased anxiety." (PMID 27065946, 2016). "The association of AI, PrL, and ovBNST with pain and anxiety is well documented." (PMID 41377021, 2025). "PRL signaling plays a pivotal role in the regulation of offspring-directed behaviors, including pup retrieval, licking, nursing, and grooming, as well as offspring-associated behaviors such as anxiety modulation, nest building, and maternal aggression." (PMID 40565372, 2025). "Importantly, elevated prolactin levels have been associated with mood disturbances, including anxiety and depressive symptoms, likely due to their influence on serotonin and dopamine pathways." (PMID 41510476, 2025). "In addition, prolactin, which also acts as a stress hormone, has been associated with multiple psychiatric disorders, such as major depression, paranoid ideation, anxiety, hostility, and somatization." (PMID 39519542, 2024). "Dysregulation of these PrL projections causes autistic-like and anxiety-like behaviors." (PMID 38503925, 2024). "Moreover, mechanistic studies indicated that elevated TNF-α/TNFR1 signaling in the PrL caused increased insertion of GluA1 receptors into PrLBLA neurons and contributed to anxiety-like behaviors in mice with chronic pain." (PMID 36917193, 2023). "In our study, thirty-six of 75 (48.0%) patients described a recent mental disorder such as anxiety, depression, or insomnia which could cause high PRL and dysfunction of hypothalamus-pituitary-ovary (HPO) axis." (PMID 33816526, 2021). "Higher cortisol and prolactin levels are associated with anxiety." (PMID 34816235, 2021). "PRL blood levels increase during acute or chronic stress (due to psychological or physiological stressors) and increased levels of PRL have been linked to emotional disorders and anxiety-related behaviors in several mammalian species." (PMID 34573561, 2021). "Even though mothers in the Preterm group markedly differed from mothers in the Term group regarding estradiol, progesterone, prolactin and the AUCg and AUCi, we only found significant associations between prolactin levels and depression as well as anxiety in mothers of preterm infants." (PMID 32296356, 2020).